Y_RNA (Y RNA )
Gene: Miscellaneous RNA gene on chromosome 6 (47,489,067 to 47,489,170, forward strand). Ensembl gene ENSG00000199762.
Homologues: Orthologues: chimpanzee Y_RNA (99% identical). Paralogues in human: Y_RNA (81% identical), RNY1P5 (79% identical), Y_RNA (79% identical), RNY1 (78% identical), Y_RNA (78% identical), Y_RNA (77% identical), Y_RNA (76% identical), Y_RNA (75% identical), RNY1P8 (74% identical), Y_RNA (74% identical), RNY1P1 (73% identical), RNY1P6 (73% identical), and 91 more.